EPCAM (epithelial cell adhesion molecule)
Diseases named in the same sentence as EPCAM in open-access papers (continued):
Sharing a sentence is not in itself a finding about the gene and the disease.
breast carcinoma (continued). "Using this strategy, we found that specific ablation of EpCAM is associated with a two-fold or greater reduction in AP-1 transcription factor activity in MDA-231 breast cancer cells at baseline, or in the presence of EGF, or PMA, which are known to induce AP-1 activity." (PMID 22132731, 2011). "EPCAM is a cell-adhesion molecule that has been associated with cell signaling, proliferation, differentiation, migration and metastasis and used as a marker of both primary tumors and circulating tumor cells for patients with breast cancers and other endothelium-derived tumors." (PMID 24944582, 2014). "Previous studies have suggested the contribution of polymorphisms in EPCAM gene to the increased risk of breast cancer and cervical cancer, and our recent study also showed that non-synonymous SNP rs1126497 in EPCAM gene may be a potential prognostic marker for NSCLC patients." (PMID 24718422, 2014). "High-level correlation between PUS7 and three key stemness-related genes (SMAD2, c-Myc, EpCAM) was further revealed in breast cancer and TNBC patients through TIMER analysis." (PMID 41554761, 2026). "The level of EpCAM expression varies among cancer types, and EpCAM-based CTC detection systems are particularly effective in malignancies with high EpCAM expression, such as prostate and breast cancers." (PMID 41459333, 2026). "Intact antibody was fragmented using pepsin proteolytic enzyme, and EpCAM Fab’ fragments were immobilized on a gold surface to detect MCF‐7 human breast cancer cells." (PMID 40951684, 2025). "To select suitable cell lines, we first assessed the expression of the epithelial molecule EpCAM and the mesenchymal protein vimentin across a panel of breast cancer cell lines by Western blot analysis." (PMID 41509313, 2025). "Fluorescent microscope analysis proved that the EpCAM Fab’ fragment exhibits a highly selective binding affinity for EpCAM‐overexpressing breast cancer cells (MCF‐7) compared to K562 (EpCAM (‐)) cells." (PMID 40951684, 2025). "EGFR (epidermal growth factor receptor) and EpCAM (epithelial cell adhesion molecule), two key cell surface markers in breast cancer, were validated as efficient cell capture targets for DTCs within microfluidic chambers." (PMID 40073025, 2025). "EpCAM overexpression promotes breast cancer invasion by activating the JNK signaling pathway and enhancing the transcriptional activity of the downstream AP-1 transcription factor." (PMID 40508038, 2025). "In vivo EpCAM-NIR-PIT in a breast cancer model in immunodeficient mice demonstrated an initial reduction in tumour size followed by delayed regrowth relative to controls." (PMID 40792441, 2025). "First, we tested the expression of EpCAM in human breast cancer using multiplex immunohistochemistry (IHC) on a tissue array of breast cancer patient samples." (PMID 40792441, 2025). "MCF7 cells were particularly well suited because EpCAM and Trop2 expression is moderately high, representative of an average range found in breast cancer and other cancer cell lines, and still in the order of magnitude of expression in normal epithelia." (PMID 39572744, 2025). "Clinical studies have shown that EpCAM is highly expressed in various cancers, including breast cancer, pancreatic cancer, various epithelial cancers, and OSCC, and its overexpression is associated with poor prognosis." (PMID 39996844, 2025). "Analysis of breast cancer patient blood by RareCyte technology revealed the clear presence of cCTCs (EpCAM+, PanCK+, CD45- cells) as well as the presence of T2CTCs." (PMID 40867346, 2025).
breast carcinoma (continued). "The selection of EGFR and EpCAM as surface markers for isolating DTCs in our study represents a targeted approach, informed by their high prevalence in specific breast cancer subtypes." (PMID 40073025, 2025). "EPCAM, expressed on the surface of breast cancer cells, is involved in cell adhesion and signaling, serving as a useful marker for cancer diagnosis and targeted therapy." (PMID 40707586, 2025). "In this study, we demonstrated the effectiveness of a surface functionalized with epithelial cell adhesion molecule (EpCAM) Fab’ (fragment‐antigen‐binding) fragments for the specific capture of EpCAM‐positive human breast cancer cells." (PMID 40951684, 2025). "First, there is a human monoclonal antibody against EpCAM, adecatumumab, which has been evaluated in clinical studies for its potential to inhibit tumor growth and metastasis in breast cancers." (PMID 39996844, 2025). "These engineered NK cells exhibit selective cytotoxicity against EpCAM-expressing breast cancer cells, suggesting their viability for targeted therapy." (PMID 40260240, 2025). "Clinical evidence suggests that EpCAM-positive CTCs play a significant role in prognostic assessment during both early and metastatic stages of breast cancer." (PMID 41372129, 2025). "CD326, also known as epithelial cell adhesion/activating molecule (EpCAM), is expressed at high levels in human breast cancers as well as 4T1, EMT‐6, and MCF‐7 cells." (PMID 40270472, 2025). "We investigate here the morphogenetic impact of the high EpCAM and Trop2 levels typically found in epithelial breast cancer cells, using spheroids of MCF7 cells as an in vitro model." (PMID 39572744, 2025). "In order to evaluate the effect of anticancer immune activation induced after NIR-PIT, we performed NIR-PIT using anti-mouse EpCAM as AbPC (mEp-NIR-PIT) against mouse breast cancer models in immunocompetent mice." (PMID 40792441, 2025). "A previous study observed EpCAM expression in 660 out of 1365 cases (48%) and reported significant variation across the different intrinsic subtypes of breast cancer." (PMID 40806559, 2025). "One of the notable targets for CAR-NK therapy in breast cancer is the epithelial cell adhesion molecule (EpCAM)." (PMID 40260240, 2025). "In order to investigate the role of EpCAM and Trop2 in collective tissue behavior, we used spheroids of breast cancer MCF7 cells as an in vitro model that mimics a solid tumor." (PMID 39572744, 2025). "We began by examining EpCAM expression in breast cancer cell lines of mice, where TUBO and 4T1 exhibited EpCAM expression, with TUBO exhibiting exceptionally high expression." (PMID 40792441, 2025). "Promoter hypomethylation of EpCAM leads to its overexpression in various tumors, such as lung cancer, endometrial cancer, breast cancer, and ovarian cancer, while emphasizing its relevance in OSCC." (PMID 39996844, 2025). "We also employed mouse breast cancer models in combination with anti-PD-1 ICI to investigate the potential for enhancing anticancer immune activation by EpCAM-targeted NIR-PIT." (PMID 40792441, 2025). "For instance, the antibody like aptamer to epithelial cell adhesion molecule (EpCAM) applomer binds specifically to EpCAM which is a biomarker predominantly over-expressed in epithelial derived neoplasms such as cancer of the breast, colon and, ovary." (PMID 40688030, 2025). "We perused with keen interest the recent article entitled ‘EpCAM-targeted near-infrared photoimmunotherapy (NIR-PIT) for the treatment of breast cancer’ published in your esteemed journal." (PMID 40964888, 2025). "Next, we evaluated anticancer immune activity induced by EpCAM-NIR-PIT with an anti-PD-1 immune checkpoint inhibitor in a mouse breast cancer model in immunocompetent mice." (PMID 40792441, 2025). "Epithelial and breast cancer-associated markers CK8 and CK18 were highly expressed in im.CTCs and epi.CTCs, while expression of E-cadherin, EpCAM, and HER2 was relatively low." (PMID 40707771, 2025).
breast carcinoma (continued). "Practical application: This study presents a preliminary design of a Fab’ fragment‐immobilized surface for the selective capture of EpCAM‐positive breast cancer cells." (PMID 40951684, 2025). "They demonstrated that the MIP recognizes breast cancer cells from epithelial cells (EpCAM expression), indicating that MIPs can be used as an additional tool to detect EpCAM-positive breast cancer cells." (PMID 39195399, 2024). "In fact, EpCAM and CD24 are associated with HER2-positive breast cancer, which can be seen from their co-expression on cell lines." (PMID 39513819, 2024). "The epithelial cell adhesion molecule EPCAM — a transmembrane glycoprotein overexpressed particularly in tumor-initiating cells (TICs) in various cancers, including breast cancer — was also more highly expressed in DAB2IP-low Luminal A tumors." (PMID 39418101, 2024). "These nanoparticles encapsulated both chemotherapeutic agents and imaging markers and exhibited an enhanced ability to target epithelial cell adhesion molecule (EpCAM)-positive MCF-7 breast cancer cells." (PMID 39063977, 2024). "In breast cancer, EpCAM-positive cells display CSC characteristics, with potential for self-renewal and differentiation, as well an enhanced tumorigenicity and migration." (PMID 38612911, 2024). "Utilizing DISVT with our machine learning-assisted image analysis platform and pilot human subjects, we demonstrate that EV’s CD24 and EpCAM can be used as biomarkers to detect breast cancer (HER2-positive) at Stages II, III, and IV." (PMID 39513819, 2024). "It is noted that the feasibility of EV’s CD24 and EpCAM to detect breast cancer needs to be validated with a larger cohort and with other molecular subtypes (i.e., hormone-positive and triple-negative breast cancer)." (PMID 39513819, 2024). "Limitation of EpCAM-based positive enrichment due to phenotypic heterogeneity of CTCs and variability in EpCAM expression, three breast cancer cell lines with differing EpCAM expressions—MDA-MB-231, MDA-MB-453, and MDA-MB-468—were selected." (PMID 38831912, 2024). "They combined it with microfluidics to form a microfluidic aptamer biosensor for analyzing breast cancer cellular epithelial cell adhesion molecule (EpCAM) in plasma." (PMID 39639411, 2024). "The use of Au NPs-EpCAM for the specific enhancement of breast cancer MDA-MB-231 exosomes is demonstrated." (PMID 38667191, 2024). "This downregulation of OPG in breast cancer cells was accompanied with an increase in the expression of the ERα protein and the epithelial markers E-cadherin and EpCAM, while the mesenchymal markers N-cadherin, Snail, and ZEB1 were downregulated." (PMID 39181873, 2024). "Through anti-EpCAM-coupled magnetic beads, exosomes are isolated and enriched in human colorectal cancer cells, ovarian cancer cells, and breast cancer cells." (PMID 38791091, 2024). "The epithelial cell adhesion molecule (EpCAM) is highly expressed in nearly all adenocarcinomas and plays a crucial role in the occurrence of the epithelial–mesenchymal transformation of breast cancer cells." (PMID 38667191, 2024). "The methylation status within the EPCAM promoter has been discussed in colon, ovarian, and breast cancer tissues and cells." (PMID 38791091, 2024). "We prepared magnetic beads conjugated with antibodies targeting specific breast cancer markers found in EVs, including epithelial cell adhesion molecules (EpCAM or CD326), CD49f, CD51, CD49b, and glypican-1 (GPC-1)." (PMID 39479442, 2024). "EpCAM has been known to be overexpressed in certain breast cancers for almost two decades and is also a marker for poor prognosis." (PMID 39513819, 2024).
breast carcinoma (continued). "Specifically, the evaluation of the proportion of CD63/EpCAM/MUC1-triplepositive EVs in breast cancer can be enhanced through the analysisof these EVs at an individual level." (PMID 39175406, 2024). "Desialylated EPCAM promotes apoptosis in breast cancer cells by activating the PI3K/AKT/mTOR signaling pathway." (PMID 39605916, 2024). "For example, compared with other subtypes, reduced expression of EpCAM is detected in the lobular subtype of breast cancer." (PMID 38791091, 2024). "With this coating and using the classical EDC/sulfo-NHS cross-linking procedure, we also demonstrate the successful multiplexed immunolabelling of Her2, CD44, and EpCAM in breast cancer cell lines (SK-BR-3 and MDA-MB-231)." (PMID 39170968, 2024). "MCF7, a breast cancer cell line, exhibited significant downregulation of EpCAM and E-cadherin expression and upregulation of N-cadherin expression following TGF-β induction." (PMID 38831912, 2024). "With respect to metastatic cancers, the expression of EpCAM is higher than that in primary tumors, including prostate cancer and breast cancer." (PMID 38791091, 2024). "These cells possessed an EPCAM + ESA + CD44 + CD24−/low phenotype that was capable of propagating mammary tumors after low-dose injections into immunodeficient mice." (PMID 39547513, 2024). "This method successfully differentiated the BT‐474 cell line, which had high expression of both HER2 and EpCAM proteins, from two other breast cancer cells (MCF‐7 and UACC) and a human mammary epithelial cell line (MCF‐10A)." (PMID 40625523, 2024). "A PEI nanocomplex was fabricated with EpCAM aptamer (EpApt) and EpCAM siRNA (siEP) to study its effects against breast cancer." (PMID 36678782, 2023). "Healthy human blood was spiked with breast cancer cells to examine the proposed platform, and the anti-EpCAM-functionalized MNs exhibited high efficiency with 94% capturing capacity in 5 min." (PMID 36979612, 2023). "We successfully generated the AAV2MEC1 vector, which specifically infected EpCAM-positive breast cancer cells in mice." (PMID 38082377, 2023). "The circulating sEV population from these patients was isolated by size exclusion chromatography, followed by analysis of EpCAM expression by flow cytometry and enrichment of breast cancer–derived sEVs using EpCAM+ beads." (PMID 36892943, 2023). "Thirdly, current studies usually focus on several aptamers including CD44, CD133, and EpCAM or several cancer types, such as glioma and breast cancer." (PMID 36969696, 2023). "The findings offer a potential gene delivery system and strategies for gene therapy targeting EpCAM-positive breast cancer and other tumor types." (PMID 38082377, 2023). "Several studies have shown the predictive value of EpCAM-based CTC assays in breast cancer and non-small cell lung cancer, which are cancers that strongly express EpCAM." (PMID 37016296, 2023). "For target protein selection, the expression of the respective targets was correlated with the EPCAM expression based on two publicly available datasets from EpCAM independently enriched breast cancer CTCs." (PMID 36823365, 2023). "This indicates that the AAV2MEC1 virus has the ability to target and infect EPCAM-positive breast cancer cells." (PMID 38082377, 2023). "Using the FDA-approved CellSearch platform, we also detected CTC (defined as EpCAM+CK+DAPI+CD45−)–neutrophil clusters in metastatic breast cancer patients." (PMID 37345070, 2023). "The CD63 protein is commonly found on most cellular exosomes, while the EpCAM protein is abundantly expressed in exosomes secreted by human breast cancer cells." (PMID 37811123, 2023). "In summary, these results demonstrate that the AAV2MEC1 vector exhibits targeted transduction capability in vivo and in vitro for EpCAM-positive breast cancer cells." (PMID 38082377, 2023).
breast carcinoma (continued). "There have been claims that when the N-glycan chain of EpCAM is disrupted in breast cancer cells, the expression of pro-apoptotic proteins Bax and Caspase 3 is increased, showing that EpCAM hinders apoptosis through its N-glycan." (PMID 36990999, 2023). "We developed an immunomagnetic assay to enrich CTCs from metastatic breast cancer patients EpCAM independently using antibodies against Trop-2 and CD-49f and characterised their EpCAM expression." (PMID 36823365, 2023). "Many studies have shown that CTCs enriched with the CellSearch system based on their EpCAM expression have a high prognostic value in metastatic as well as early breast cancer." (PMID 36823365, 2023). "The epithelial cell adhesion molecule (EpCAM) is highly expressed in various tumor cells, including those of breast cancer." (PMID 38082377, 2023). "Based on the obtained results, it was found that both EpCAM+ and HER2 + sEVs can be effective diagnostic markers of breast cancer." (PMID 37504087, 2023). "The epithelial cell adhesion molecule (EpCAM) is highly expressed in various tumor cells, including breast cancer cells." (PMID 38082377, 2023). "It was found that EpCAM expression evaluated by the microfluidic chip allows differentiating of breast cancer patients from control patients with 90% sensitivity and >95% specificity." (PMID 37504087, 2023). "The fabricated PEI-EpApt-siEp knocked down EpCAM and subdued the proliferation of breast cancer cells MCF-7." (PMID 36678782, 2023). "Previous studies indicated that breast cancer stem cells with specifics markers include CD44positive, CD24negative, EpCAM positive, and CD133 positive." (PMID 37620448, 2023). "Next, EDFs were collected from seven samples from metastatic breast cancer patients and tumour cells therefrom were in parallel enriched both EpCAM dependently and independently." (PMID 36823365, 2023). "EpCAM was upregulated in both primary and metastatic breast cancers, and silencing the EpCAM gene inhibited the proliferation, migration, and invasion of certain BC cell lines." (PMID 37457288, 2023). "Accurate identification of three breast cancer cell biomarkers including EpCAM, ErbB2, and CD44 was achieved by using PEGylated Ag–Au hollow nanospheres based on Raman imaging." (PMID 37323623, 2023). "HCC38 sorted breast cancer cells – Excel spreadsheet containing the CIN enrichment scores for HCC38 breast cancer cells sorted according to their cell surface EpCAM (Ep) and integrin αvβ3 (b3) status from three independent experiments." (PMID 37840990, 2023). "To evaluate the targeted transduction capability of AAV2MEC1 in vivo on EpCAM-positive breast cancer cells 4T-1, we subcutaneously injected 2.5 × 10^5 4T-1 cells into the back of each BALB/c female mice." (PMID 38082377, 2023). "Deglycosylated EpCAM enhances autophagy of cancer cells via PI3K/Akt/mTOR pathway in breast cancer cells." (PMID 37834237, 2023). "Single mutations were identified in MEN1 for gastric cancer, MSH6 for colorectal cancer, CDKN2A for pancreatic cancer, and EPCAM/TSC2/GALNT12 for breast cancer." (PMID 38201513, 2023). "This EpCAM-AAV was proven to effectively identify EpCAM-positive breast cancer cells, specifically MDA-MB-453, in an in vitro setting." (PMID 38082377, 2023). "We have demonstrated that deglycosylated-EpCAM strengthened the cytotoxic effect of 5-FU and promoted apoptosis in breast cancer cells." (PMID 34983878, 2022). "This breast cancer subtype is suggested to be characterized by low EpCAM expression, which has led to numerous reports of a lower isolation performance of the CellSearch platform." (PMID 35397078, 2022). "Through the experiment, the levels of HER2 and EpCAM in the exosomes of MCF-7 breast cancer cells were the highest, which is consistent with the biomarkers of breast cancer reported in papers, thus proving the application value of ASPNC." (PMID 36235208, 2022).